RN7SL498P (RNA, 7SL, cytoplasmic 498, pseudogene)
Gene: Miscellaneous RNA gene on chromosome 20 (6,001,733 to 6,002,030, forward strand). Ensembl gene ENSG00000263755.
Homologues: Orthologues: chimpanzee Metazoa_SRP (98% identical), macaque Metazoa_SRP (85% identical). Paralogues in human: RN7SL1 (86% identical), RN7SL2 (85% identical), RN7SL3 (85% identical), RN7SL11P (82% identical), RN7SL301P (82% identical), RN7SL88P (82% identical), RN7SL566P (81% identical), Metazoa_SRP (81% identical), RN7SL627P (81% identical), RN7SL630P (81% identical), RN7SL664P (81% identical), RN7SL113P (81% identical), and 698 more.